WNT11 (Wnt family member 11)
Diseases named in the same sentence as WNT11 in open-access papers (continued):
Sharing a sentence is not in itself a finding about the gene and the disease.
COVID-19 (3 papers, 2022 to 2024). A disease caused by infection with severe acute respiratory syndrome coronavirus 2. "According to this report, Wnt5a level was significantly higher and Wnt11 level was significantly lower in patients with severe or fatal COVID-19." (PMID 38584257, 2024). "Interestingly, Wnt5a and Wnt11 have been suggested to be potential biomarkers of COVID-19 severity, with high levels of Wnt5a correlated to poor prognosis and increased Wnt11 expression indicating efficient inhibition of inflammatory responses caused by SARS-CoV-2 infection." (PMID 38203386, 2023). "Regarding to our findings, a recent study has shown the relation of canonical Wnt/β-catenin pathway with inflammatory responses, which is based on the observation of Wnt5a and Wnt11, as ARDS biomarkers, released from immune cells in patients with COVID-19." (PMID 38584257, 2024).
diabetes (3 papers, 2021 to 2025). "We excluded the factors about smoke and diabetes and found serum Wnt5a and Wnt11 levels positively correlated to E/e′ (Wnt5a: r = 0.455, p = 0.010; Wnt11: r = 0.480, p = 0.006)." (PMID 34564708, 2021).
fibrosis (3 papers, 2021 to 2025). the formation of excess fibrous connective tissue in an organ or tissue in a reparative or reactive process. "LRP6 overexpression reduced the expression and secretion of Wnt5a and Wnt11 by cardiomyocytes, and knockdown of Wnt5a and Wnt11 greatly inhibited cardiac fibrosis and dysfunction under pressure overload in vitro and in vivo." (PMID 33391533, 2021). "Cardiomyocyte-expressed LRP6 interacted with cathepsin D (CTSD, a protease) and promoted the degradation of Wnt5a and Wnt11, inhibiting cardiac fibrosis and dysfunction induced by TAC." (PMID 33391533, 2021). "In conclusion, pressure overload enhances the secretion of Wnt5a or Wnt11 from CMs and CFs which promotes cardiac fibrosis by activation the crosstalk of FZD5 and EGFR." (PMID 34564708, 2021). "The knockdown of Wnt5a and Wnt11 significantly inhibited cardiac fibrosis under pressure overload." (PMID 33391533, 2021). "However, few evidences indicate that Wnt5a or Wnt11 directly promotes cardiac fibrosis during chronic pressure overload." (PMID 34564708, 2021).
myocardial infarction (3 papers, 2016 to 2023). Gross necrosis of the myocardium, as a result of interruption of the blood supply to the area, as in coronary thrombosis. "When focusing on the early post-myocardial infarction (MI) phase, quantitative analyses of Wnt protein expression have unveiled notable upregulation of Wnt-2, Wnt-4, Wnt-10b, and Wnt-11 five days after MI." (PMID 38139379, 2023). "Indeed, Analysis of the expression of Wnt proteins indicated that Wnt-2, Wnt-4, Wnt-10b, and Wnt-11 were significantly upregulated 5 days after myocardial infarction." (PMID 36072583, 2022). "However, we clearly showed the beneficial therapeutic effects of Wnt11 for myocardial infarction." (PMID 26882996, 2016).
prostate tumor (3 papers, 2010 to 2020). "Wnt-11 protein levels are elevated in patient tumors; we used anti-Wnt-11 antibodies to localize Wnt-11 expression in sections taken from prostate tumor tissue samples." (PMID 32182839, 2020). "Our results suggest that Wnt-11 can endow prostate tumour cells with three properties important for PCa progression, namely, increased resistance to apoptosis, neuroendocrine-like differentiation and increased motility." (PMID 20219091, 2010). "Wnt-11 protein levels in prostate tumours were determined by immunohistochemical analysis of prostate tumour tissue arrays." (PMID 20219091, 2010). "This was unexpected given the high level of expression of Wnt-11 in some high-grade tumours as well as in all prostate tumour bone metastases examined." (PMID 20219091, 2010). "This study shows that Wnt-11 protein levels are elevated in a significant proportion of human prostate tumours." (PMID 20219091, 2010). "In order to determine whether Wnt-11 protein levels are elevated in patient tumours, we used anti-Wnt-11 antibodies to localise Wnt-11 expression in sections taken from human prostate and prostate tumour tissue." (PMID 20219091, 2010). "Finally, Wnt-11 and AR were found to be co-expressed in prostate tumour cells." (PMID 20219091, 2010). "We further show that both Wnt-11 and FZD8 protein levels are higher in prostate tumor cells than in prostate epithelial cells in benign tissue, consistent with a role for FZD8 in transducing autocrine Wnt-11 signals." (PMID 29717114, 2018). "FZD10 mRNA was only detected in VCaP cells, which express the highest level of Wnt-11, suggesting that FZD10 may be a functional Wnt-11 receptor in a subset of prostate tumors." (PMID 29717114, 2018). "However, FZD2 mRNA levels were not upregulated in prostate tumor datasets and FZD2 did not co-localize with Wnt-11 in PC-3M cells." (PMID 29717114, 2018).
renal hypoplasia (3 papers, 2009 to 2025). Renal hypoplasia is a developmental anomaly in which one or both kidneys (unilateral or bilateral renal hypoplasia, respectively) have a deficit in the number of nephrons and may be small. "This is supported by our genetic experiments in which lowering UB-expressed Wnt11 expression in the Gdnfhyper/hyper background improved NP maintenance and differentiation, but failed to fully rescue the renal hypoplasia caused by the excess GDNF." (PMID 34032268, 2021). "Therefore, biallelic WNT11 dysfunction should be considered a novel genetic cause of syndromal human phenotypes presenting with congenital heart defects and renal hypoplasia, with or without laterality defects." (PMID 40200693, 2025). "Furthermore, we did not identify any additional likely disease-causing WNT11 variants using exome sequencing in a cohort of 37 cases with laterality defects or in three additional cases with renal hypoplasia." (PMID 40200693, 2025).
glioma (2 papers, 2016). A benign or malignant brain and spinal cord tumor that arises from glial cells (astrocytes, oligodendrocytes, ependymal cells). "Piezo2 could regulate glioma angiogenesis via Ca2+/Wnt11/β-catenin signaling in endothelial cells." (PMID 27329839, 2016).
liver cancer (2 papers, 2020 to 2021). An epithelial or non-epithelial malignant neoplasm that arises from the liver.
liver fibrosis (2 papers, 2016 to 2021). "In the current study, the Hh-related genes, including Bmp4, Gas1, Gli3, Hhip, Ihh, Prkacb, Stk36, Wnt6, Wnt10b, Wnt9a and Wnt11, were dysregulated in our murine model of CCl4-induced liver fibrosis." (PMID 27322257, 2016).
mucinous adenocarcinoma (2 papers, 2019 to 2024). An invasive adenocarcinoma composed of malignant glandular cells which contain intracytoplasmic mucin. "As expected, there was a significant association of Wnt-11 with the presence of adenocarcinoma (p = 0.006), and this was also observed for mucinous adenocarcinoma (p = 0.025)." (PMID 31261741, 2019). "Significant results (P< 0.05) included associations with WNT11 and FBXL16 and body mass index (BMI), MSLN and mucinous adenocarcinoma, and SLC38A11 and metastasis." (PMID 38680862, 2024).
myocarditis (2 papers, 2016 to 2019). Myocarditis is a condition that is characterized by inflammation of the heart muscle (myocardium). "Other targets may also include Wnt11, in which mir-154-5p targets Wnt11 during osteogenic differentiation and improves cardiac function in Coxsackievirus induced myocarditis, and DiGeorge syndrome, but the specific role of mir-154-5p on Wnt11 in DCM is still unknown." (PMID 30792263, 2019).
osteoporosis (2 papers, 2023 to 2024). A condition of reduced bone mass, with decreased cortical thickness and a decrease in the number and size of the trabeculae of cancellous bone (but normal chemical composition), resulting in increased fracture incidence. "Wnt11, a new gene associated with early onset osteoporosis and the main Wnt ligand related to bone fragility and EOOP, which mutations in this gene were described to be related to autosomal dominant osteoporosis, is required for osteoblastogenesis." (PMID 38098062, 2023).
rectal cancer (2 papers, 2019 to 2025). A primary or metastatic malignant neoplasm that affects the rectum. "We also noted an inverse relationship between Wnt-11 and the Charlson Comorbidity Index, a factor for poor prognosis in rectal cancer patients in Spain and in this patient cohort." (PMID 31261741, 2019).
squamous cell carcinoma (2 papers, 2021 to 2025). A carcinoma arising from squamous epithelial cells. "The expression profile of WNT11 was checked in other types of squamous cell carcinoma such as lung (LUSC) and esophageal cancers (ESCC)." (PMID 33840169, 2021).
aneurysm (1 paper, 2022). Bulging or ballooning in an area of an artery secondary to arterial wall weakening. "In our other dataset (GSE54083), we were surprised to find that the expression of CDH11, SPARC, FN1, and FSTL1 in unruptured aneurysms was significantly increased, while WNT11, PCDH9, and GPC3 expression levels were relatively low." (PMID 34997174, 2022). "It was found that the expression levels of CDH11, SPARC, FN1, and FSTL1 genes in unruptured aneurysms were higher than those in healthy samples, while the expression levels of WNT11, PCDH9, and GPC3 in unruptured aneurysms were lower than those in healthy samples." (PMID 34997174, 2022).
angioleiomyoma (1 paper, 2018). A benign, slow-growing neoplasm that arises from the dermis or subcutaneous tissue. "Only six genes show significant differences between the angioleiomyoma types (ISL1, NCSTN, TCF7, WNT10A, WNT11, WNT7A) but their relative expression levels were very low, which indicates no biological relevance (< 0.4 compared to standardized reference gene index)." (PMID 29881541, 2018).
atrial fibrillation (1 paper, 2025). A disorder characterized by an electrocardiographic finding of a supraventricular arrhythmia characterized by the replacement of consistent P waves by rapid oscillations or fibrillatory waves that vary in size, shape and timing and are accompanied by an irregular ventricular response. "In a research including patients with rheumatic valve disease undergoing valve surgery, atrial fibrillation was associated with increased expression of the transcription factor SNAIL1 and other WNT ligands, including the non-canonical WNT ligands WNT5A and WNT11, in the right atrium." (PMID 39482911, 2025). "In research including patients with rheumatic valve disease undergoing valve surgery, atrial fibrillation was associated with increased expression of the transcription factor SNAIL1 and other WNT ligands, including the non-canonical WNT ligands WNT5A and WNT11, in the right atrium." (PMID 39482911, 2025).
benign prostatic hypertrophy (1 paper, 2010). "Wnt-11 protein was elevated in 77/117 of tumours when compared with 27 benign prostatic hypertrophy specimens and was present in 4/4 bone metastases." (PMID 20219091, 2010).
bone sarcoma (1 paper, 2015). A sarcoma that arises from the bone. "Our results have illuminated that Wnt11 was remarkably increased in bone sarcoma cells, suggesting Wnt11 as an oncogenic role during bone sarcomagenesis." (PMID 25999350, 2015). "In contrast, among noncanonical Wnt ligands, the expression of Wnt5a, Wnt5b and Wnt16 was either decreased or lost in bone sarcoma cells; however, Wnt6, Wnt7b, and Wnt11 were remarkably increased in bone sarcoma cells." (PMID 25999350, 2015). "Clearly, further studies are needed to determine the primary function of Wnt6, Wnt7b and Wnt11 in bone sarcomas." (PMID 25999350, 2015). "In contrast, the noncanonical Wnt6, Wnt7b, and Wnt11 were significantly increased in bone sarcoma cells." (PMID 25999350, 2015).
breast tumors (1 paper, 2025). "Similarly, WNT2 and WNT7B were highly upregulated, whereas WNT11 was highly downregulated in HER2-positive breast tumors compared with that in the control tissue." (PMID 41044153, 2025).
chronic myeloid leukemia (1 paper, 2019). "In humans, the Wnt11 promoter contains a conserved Kaiso-binding site (at -775), and experimental laboratory results have indicated cooperation between β-catenin/TCF and Kaiso/p120ctn in the negative regulation of Wnt11 transcription in chronic myeloid leukemia (CML)." (PMID 30940992, 2019).
colitis (1 paper, 2022). Inflammation of the colon. "Recently, we investigated the nuclear factor of activated T cell (NFAT), a downstream molecule of the noncanonical Wnt signaling expression including Wnt5a and Wnt11 in a dextran sulfate sodium (DSS)-induced colitis (DIC) model, suggesting a potential proinflammatory role in the pathogenesis of IBD." (PMID 36144473, 2022).
Cushing syndrome (1 paper, 2021). Cushing's syndrome (CS) encompasses a group of hormonal disorders caused by prolonged and high exposure levels to glucocorticoids that can be of either endogenous (adrenal cortex production) or exogenous (iatrogenic) origin. "For example, WNT11, WNT9A, and FZD9 were all enriched in cancer signaling pathways, the Cushing syndrome signaling pathway, and the Wnt signaling pathway." (PMID 34737761, 2021).
cutaneous melanoma (1 paper, 2023). A primary melanoma arising from atypical melanocytes in the skin. "FAKi treatment robustly decreased TCF-4 binding to the CCND1 and C-myc promoters and induced a moderate decrease of WNT-11 and S1PR1 promoters, in concordance with the TCGA analysis in UM and cutaneous melanoma patients." (PMID 36797281, 2023).
cyst (1 paper, 2013). A sac-like closed membranous structure that may be empty or contain fluid or amorphous material. "Remarkably, in addition to cyst formation, loss of primary cilia in the ureteric epithelial cell leads to decreased expression of Wnt11 and Ret and reduced ureteric branching." (PMID 23762375, 2013).
cystic kidney disease (1 paper, 2016). A congenital or acquired kidney disorder characterized by the presence of renal cysts. "Given the Wnt11 deficiency dependent changes in the kidney tubular system we also examined possible changes in the genes encoding the “core” PCP pathway and certain other genes (e.g. TCS2, PDK1 and HNF1b) involved in cystic kidney diseases by qRT-PCR using E16.5 and NB kidneys." (PMID 27582005, 2016).
disc degeneration (1 paper, 2020). "The specific mechanism of Wnt11 involvement in the aging of NP cells and disc degeneration is still unclear, and whether nonclassical Wnt pathways are involved in this process requires further research and exploration." (PMID 32025238, 2020).
embryonic carcinoma (1 paper, 2012). "A major role for Wnt11 in vivo is its ability to promote differentiation, for example, stimulating cardiac differentiation of mouse embryonic carcinoma P19 cells, and promoting differentiation of many different types of cells." (PMID 22709531, 2012).
human papillomavirus infection (1 paper, 2023). "Further, downregulation of the Wnt11 dependent branches in Brest Cancer and human papillomavirus infection pathways indicated reduced signaling within Wnt/β-Catenin signaling." (PMID 37887323, 2023).
Hypertension (1 paper, 2021). The presence of chronic increased pressure in the systemic arterial system. "Serum Wnt5a or Wnt11 was elevated and associated with diastolic dysfunction in hypertension patients." (PMID 34564708, 2021). "Inhibition of Wnt5a or Wnt11 may have therapeutic potential for the prevention of cardiac fibrosis associated with hypertension or pressure overload." (PMID 34564708, 2021). "Serum Wnt5a and Wnt11 levels were examined in patients with hypertension (HBP) and the control group." (PMID 34564708, 2021). "Here, we aimed to explore serum Wnt5a and Wnt11 levels in hypertension patients, the roles of Wnt5a and Wnt11 in cardiac fibrosis and potential mechanisms under pressure overload." (PMID 34564708, 2021). "We then analyzed the relationship between serum Wnt5a or Wnt11 level and echocardiographic parameters of hypertension patients and the control group." (PMID 34564708, 2021). "In the present study, we revealed that serum Wnt5a and Wnt11 were increased in patients with hypertension as compared to healthy controls." (PMID 34564708, 2021).
ischemia (1 paper, 2020). A hypoperfusion of the BLOOD through an organ or tissue caused by a PATHOLOGIC CONSTRICTION or obstruction of its BLOOD VESSELS, or an absence of BLOOD CIRCULATION. "Wnt11 protein was significantly reduced in the myocardium after the heart underwent ischemia for 8 h in a time-dependent manner." (PMID 33137935, 2020).
kidney failure (1 paper, 2016). An acute or chronic condition that is characterized by the inability of the kidneys to adequately filter the blood. "Together these results indicate that Wnt11 deficiency leads to a moderate degree of kidney failure and indicates a role for Wnt11 in the assembling of a functional kidney." (PMID 27582005, 2016). "Blood and urine analyses of Wnt11−/− mice indicated moderate kidney failure." (PMID 27582005, 2016).
lung carcinoma (1 paper, 2023). "In short, WNT11 is mainly carcinogenic in the development of lung cancer, and inhibiting its overexpression may aid the treatment of this disease." (PMID 37486552, 2023). "Recently, Ito and colleagues found that the increased acetylation level of H3K27, an enhancer of the WNT11 gene caused by the upregulation of ASCL1 and its recruitment to oncogenic SOX2 may be an initiating factor in the cause of WNT11 upregulation and resultant progression of lung cancer." (PMID 37486552, 2023). "WNT11 is also lowly expressed in chemo-resistant SCLC cells, indicating its upregulation may contribute to the treatment of lung cancer." (PMID 37486552, 2023).
malignant glioma (1 paper, 2016). A grade III or grade IV glioma arising from the central nervous system. "Using an orthotopic malignant glioma model in which U87ΔEGFR cells are injected into the frontal lobe of athymic mice, we observed increased expression of WNT11 mRNA in animals treated with bevacizumab." (PMID 26861754, 2016). "Finally, elevated WNT11 expression was observed in the hypoxic area of allograft tumors and in human malignant glioma xenografts after treatment with antiangiogenic therapy." (PMID 26861754, 2016). "In addition, in mice bearing orthotopic malignant gliomas, inhibition with bevacizumab of vascular endothelial growth factor, which is an important stimulus for angiogenesis, increased nuclear HIF-1α and HIF-2α, and expression of WNT11." (PMID 26861754, 2016).
metastatic cancer (1 paper, 2019). A carcinoma which has spread from the original site of growth to another anatomic site. "A more relevant difference among the CRC cell lines examined, perhaps, is that COLO 205 and LoVo cells are derived from metastases, whereas HCT116 and HT29 cells are from primary tumors, suggesting Wnt-11 plays a role in metastatic cancer." (PMID 31261741, 2019).
metastatic disease (1 paper, 2022). "Wnt11 is known to be activated during embryogenesis and it is upregulated in a wide range of malignancies and especially in metastatic disease." (PMID 35668332, 2022).
metastatic prostate carcinoma (1 paper, 2018). A carcinoma that arises from the prostate gland and has spread to other anatomic sites. "Together, these observations are consistent with FZD8 as a receptor of Wnt-11 in metastatic prostate cancer." (PMID 29717114, 2018).
muscular disease (1 paper, 2024). Myopathy is a peripheral nervous system disease consisting of any abnormal condition or disease of the muscular tissues; commonly designates a disorder involving skeletal muscle. "It will be of interest to examine how much extents Ror2 signaling, activated synergistically by Wnt5b and Wnt11, will contribute to the progression of muscular diseases accompanied with IMAT accumulation including DMD and sarcopenia." (PMID 39468010, 2024).